PC (pyruvate carboxylase)
Diseases named in the same sentence as PC in open-access papers (continued):
Sharing a sentence is not in itself a finding about the gene and the disease.
Hypoglycemia (3 papers, 2019 to 2023). A decreased concentration of glucose in the blood. "Further, under hypoxic conditions mice develop hypoglycemia, as evidenced by decreased pyruvate levels (despite increased gluconeogenic amino acid levels), decreased pyruvate carboxylase levels, and a decreased expression of gluconeogenic amino acid processing enzymes." (PMID 37747892, 2023). "Hypoglycemia can be due to the inhibition of different pathways: of mitochondrial β-oxidation via the inhibition of CPT-I by malonyl-coA, of pyruvate carboxylase secondary to dicarboxylic aciduria, and of the tricarboxylic acid cycle via the inhibition of succinic acid dehydrogenase by malonic acid." (PMID 34884438, 2021).
liver steatosis (3 papers, 2021 to 2025). "The activity of lipid biosynthesis enzymes acetyl CoA carboxylase 1 (ACC1) and pyruvate carboxylase (PC) is linked to liver steatosis." (PMID 39920308, 2025). "Furthermore, selective inhibition of pyruvate carboxylase expression in liver and adipose tissue significantly reduced adiposity, plasma lipid levels and hepatic steatosis." (PMID 33708149, 2021). "The increased gluconeogenesis has been shown to originate from oxaloacetate (from the pyruvate carboxylase reaction), with possible contributions from pyruvate, lactate and amino acids, while gluconeogenesis from glycerol, on the other hand, seems to be diminished in liver steatosis." (PMID 33498493, 2021). "The kinesin KIF12 protects against liver steatosis and cirrhosis by promoting the ubiquitination and degradation of two lipogenic enzymes: ACC1 and PC." (PMID 39920308, 2025). "By the use of stable propionate tracers and MR Spectroscopy in obese individuals with liver steatosis, the TCA cycle flux and pyruvate carboxylase flux (conversion of pyruvate to oxaloacetate) were elevated when compared with obese controls without steatosis." (PMID 33498493, 2021).
Lymph Node Metastasis (3 papers, 2021 to 2022). "Recently, we have shown that PC protein is also overexpressed in colorectal tissue of CRC patients, in which a high level of PC was associated with advanced tumor stage, perineural invasion, lymph node metastasis, and poor prognosis." (PMID 36439442, 2022).
prostate carcinoma (3 papers, 2016 to 2019). A carcinoma that arises from epithelial cells of the prostate gland. "Further investigations on the pathophysiologic effects of PC-1 on AR function may reveal that PC-1 can serve as a valuable target in controlling prostate cancer progression." (PMID 27835608, 2016). "Therefore, we investigated the potential role of PC-1/PrLZ for increasing radioresistance in human prostate cancer cell lines." (PMID 27694690, 2016). "Moreover, suppression of endogenous PC-1/PrLZ radiosensitized prostate cancer cells, contributing to increased induction of autophagic cell death but not apoptosis and senescence after IR." (PMID 27694690, 2016). "Moreover, recent evidence indicates that PC-1/PrLZ is frequently overexpressed in advanced prostate cancer tissues, and this increased expression contributes to malignant phenotypes, including androgen-dependent and-independent growth, anchor-independent growth and tumorigenicity." (PMID 27694690, 2016). "This implies that the CRPC associated increased PC-1 expression may not respond due to AR variants that lack the hinge region being able to potentially escape PC-1-mediated degradation, thus maintaining high transcriptional activity and contributing to prostate cancer progression." (PMID 27835608, 2016). "PC-1/PrLZ, a TPD52 protein family member is frequently upregulated in advanced prostate cancer cells and may be a biomarker of aggressive prostate cancer." (PMID 27694690, 2016). "Our present study revealed that PrLZ/PC-1 didn't increase IR induced senescence in prostate cancer cells, suggesting PrLZ/PC-1 might did not regulate other mTOR signal downstream targets which were correlated with senescence regulation." (PMID 27694690, 2016).
thyroid cancer (3 papers, 2021 to 2025). "experimentally verified that pyruvate carboxylase is closely associated with tumor aggressiveness in thyroid cancer by stimulating fatty acid synthesis." (PMID 40963858, 2025). "Previous studies have shown that pyruvate carboxylase (PC) plays a key role in the occurrence and progression of thyroid cancer (TC); however, the relationship between PC and iodine-refractory TC is unclear." (PMID 36266265, 2022). "Although PC overexpression has been observed in thyroid cancer (TC), the mechanisms involved in the carcinogenic effects of PC are still unclear." (PMID 34158007, 2021).
atherosclerosis (2 papers, 2014 to 2025). A disease characterized by the build-up of fatty material and calcium deposition in the arterial wall resulting in partial or complete occlusion of the arterial lumen. "This study investigates the role of macrophage pyruvate carboxylase (PC) in atherosclerosis (AS) demonstrating that PC upregulation in macrophages promotes metabolism reprogramming to enhance inflammatory responses via the HIF‐1 signaling pathway." (PMID 40391718, 2025). "Above 90th percentile, anti-OxCL (p = 0.044), anti-OxPS (p = 0.0239), and anti-PC (p = 0.0284) were protection markers for atherosclerosis development." (PMID 25473948, 2014).
autosomal dominant polycystic kidney disease (2 papers, 2015 to 2020). Autosomal dominant form of polycystic kidney disease. "Various mutations in the genes that code for PC-1 and PC-2 can result in autosomal dominant polycystic kidney disease (ADPKD), which is the most common monogenetic disease in humans." (PMID 33164752, 2020). "Mutations in the polycystin proteins, PC-1 and PC-2, result in autosomal dominant polycystic kidney disease (ADPKD) and ultimately renal failure." (PMID 33164752, 2020). "The prototype CKD is autosomal dominant polycystic kidney disease (ADPKD), whose mutated genes encode for two membrane-bound proteins, polycystin-1 (PC-1) and polycystin-2 (PC-2), of unknown function." (PMID 26529018, 2015).
brain tumors (2 papers, 2019 to 2022). "Of note, we did not detect increased expression in medulloblastoma compared to other pediatric brain tumors of mRNA for pyruvate carboxylase (which would allow direct incorporation of pyruvate carbons to oxaloacetate) or any of the other TCA cycle or urea cycle enzymes)." (PMID 35267619, 2022).
colorectal cancer (2 papers, 2022 to 2024). A primary or metastatic malignant neoplasm that affects the colon or rectum. "We have recently shown that overexpression of PC protein was associated with staging, metastasis and poor survival of colorectal cancer patients." (PMID 36439442, 2022).
COVID-19 (2 papers, 2021 to 2025). A disease caused by infection with severe acute respiratory syndrome coronavirus 2. "Our analysis revealed that genes coding for pyruvate carboxylase (pyc) had several-fold overexpression in the microbiomes of the COVID-19 (26.31%) and Recovered (4.11%) groups compared to Healthy controls (1.80%)." (PMID 34911967, 2021). "Cg17126990 (annotated to AFAP1L2) and cg25483596 (annotated to PC) were the common CpG sites identified to be differentially methylated across the different study approaches, thus suggesting their relevance in the aftermath of COVID-19." (PMID 40251596, 2025).
lactic acidosis (2 papers, 2022 to 2023). Metabolic acidosis characterized by the accumulation of lactate in the body. "Lactic acidosis from MET is caused by inhibition of gluconeogenesis by blocking pyruvate carboxylase, which leads to accumulation of lactic acid." (PMID 37653564, 2023).
lung adenocarcinoma (2 papers, 2021 to 2022). A carcinoma that arises from the lung and is characterized by the presence of malignant glandular epithelial cells. "A previous study has shown that piR-hsa-211106 inhibits the progression of lung adenocarcinoma and enhances chemotherapy sensitivity by pyruvate carboxylase." (PMID 36249068, 2022).
melanoma (2 papers, 2020 to 2023). A malignant, usually aggressive tumor composed of atypical, neoplastic melanocytes. "Interestingly, in melanoma the contribution of pyruvate carboxylase to the TCA cycle is very low." (PMID 32528879, 2020). "Differently from melanoma, other glycolytic tumors replenish the TCA cycle of precursors through the action of enzyme pyruvate carboxylase which produces oxaloacetate from pyruvate." (PMID 32528879, 2020). "Interestingly, melanoma TCA is not replenished by precursors through the anaplerotic enzyme pyruvate carboxylase but glutamine is the major source." (PMID 37160873, 2023).
metastatic tumor (2 papers, 2022 to 2023). "The increased pyruvate carboxylase and high proliferation rates of metastatic tumors could be associated with the promoted utilization of pyruvate, which led to the decreased serum pyruvate level found in metastatic mice." (PMID 36677035, 2023). "Moreover, pyruvate carboxylase (PC) which is essential for primary and metastatic tumor growth catalyzes pyruvate to the TCA cycle metabolite oxaloacetate." (PMID 36035161, 2022). "To understand the detailed changes in the cellular system between primary tumors and metastatic tumors, we conducted H&E staining, immunofluorescence staining of Ki-67, and Western blotting of Glut1, HK1, HK2, PKM2, and PC." (PMID 36677035, 2023).
paraganglioma (2 papers, 2017 to 2022). A benign or malignant neoplasm arising from paraganglia located along the sympathetic or parasympathetic nerves. "Another example for this concept is demonstrated by the effectiveness of a pyruvate carboxylase (PC) knockdown to impair the proliferation of paraganglioma with mutation in succinate dehydrogenase (SDH)." (PMID 28725214, 2017).
renal fibrosis (2 papers, 2025). A final common manifestation of a wide variety of chronic kidney diseases characterized by glomerulosclerosis and tubulointerstitial fibrosis. "In this study, we provided clinical and molecular evidence suggesting that PC deficiency in RTECs may contribute to CKD and renal fibrosis." (PMID 39836535, 2025).
Sepsis (2 papers, 2021 to 2025). Sepsis is defined as life-threatening organ dysfunction caused by a dysregulated host response to infection. "Potential reasons for impaired lactate‐driven gluconeogenesis in sepsis include reduced activity of essential enzymes involved in gluconeogenesis (i.e., pyruvate carboxylase, phosphoenolpyruvate carboxy kinase)." (PMID 40474781, 2025). "We confirmed the role of pyruvate carboxylase during infection by using our genetically complemented strain and the pyc mutant with our murine sepsis model, which showed the most profound defect in infection compared to pneumonia and skin models." (PMID 34101490, 2021).
viral infection (2 papers, 2017 to 2021). "Overall, the results demonstrate that antibody response to gB, gH/gL, and PC is important for effective neutralization of virus infection." (PMID 34452332, 2021).
bipolar disorder (1 paper, 2021). A disorder of the brain that causes unusual shifts in mood, energy, activity levels and the ability to carry out day-to-day tasks. "The potential connection between the efficacy of carbamazepine in bipolar disorder treatment and its effect on pyruvate carboxylase has yet to be investigated." (PMID 33708149, 2021). "We propose that the elevated glutamate levels in bipolar disorder can be explained by increased pyruvate carboxylase-mediated anaplerosis in brain." (PMID 33708149, 2021). "In this work we propose that the elevated brain glutamate levels in bipolar disorder observed by 1H MRS with very high consistency can be explained by an increase in pyruvate carboxylase-mediated anaplerosis." (PMID 33708149, 2021). "Increased pyruvate carboxylase-mediated anaplerosis can readily explain the elevated glutamate or glutamate + glutamine levels in brain in bipolar disorder observed by in vivo1H MRS." (PMID 33708149, 2021). "However, several drugs used in the treatment of bipolar disorder have important links to pyruvate carboxylase." (PMID 33708149, 2021). "The pyruvate carboxylase-mediated anaplerotic pathway may represent future therapeutic targets for bipolar disorder." (PMID 33708149, 2021). "Therefore, the elevated glutamate + glutamine levels are consistent with mitochondrial dysfunction and a chronic mismatch between glucose utilization and oxidative metabolism in bipolar disorder accompanied by incomplete carbohydrate oxidation and increased pyruvate carboxylase-mediated anaplerosis." (PMID 33708149, 2021). "Despite the highly reproducible evidence of elevated brain glutamate levels in bipolar disorder from numerous in vivo MRS studies, to the best of our knowledge, a connection between the MRS results and pyruvate carboxylase-mediated anaplerosis has not been made in the literature." (PMID 33708149, 2021).
chondrosarcoma (1 paper, 2021). A malignant cartilaginous matrix-producing mesenchymal neoplasm arising from the bone and soft tissue. "Alanine (Ala), glycine (Gly), and serine (Ser), which are broadly elevated in mutant IDH chondrosarcomas, enter pathways of energy production via pyruvate, which in turn can be oxidized via pyruvate dehydrogenase or used as an anaplerotic substrate to generate oxaloacetate via pyruvate carboxylase." (PMID 33762012, 2021).
chronic hepatitis B (1 paper, 2007). "Our results indicate that the presence of BCP and PC mutations significantly increases the risk for HCC in chronic hepatitis B patients." (PMID 17900245, 2007).
co-infection (1 paper, 2018). "In respect to PC mutations, co-distribution of the overall PC mutations and ADV resistance gene variants (rtQ215H and rtI233V) were common during HIV co-infection." (PMID 29408943, 2018).
colitis (1 paper, 2021). Inflammation of the colon. "The effect of colitis on glucose level was studied by measurement of fasting glucose and GLP-1, dipeptidyl peptidase IV (DPP IV) levels, prohormone convertase 1/3 (PC 1/3) and GLP-1 receptor (GLP-1R) expression in mice." (PMID 34535873, 2021).
colon adenocarcinoma (1 paper, 2017). "We also looked at other genes involved in pyruvate transport and metabolism and interestingly, MPC1, MPC2, PDHA1 and PC showed consistent downregulation in a specific subset of colon adenocarcinomas known as colon mucinous adenocarcinomas (AC) (n = 22)." (PMID 28397687, 2017).
Crohn disease (1 paper, 2025). A gastrointestinal disorder characterized by chronic inflammation involving all layers of the intestinal wall, noncaseating granulomas affecting the intestinal wall and regional lymph nodes, and transmural fibrosis. "In addition, GrpE protein homolog 1, 39S ribosomal protein L33, and tRNA pseudouridine synthase A are pathogenic in Crohn's disease, and Hydroxymethylglutaryl‐CoA synthase and Pyruvate carboxylase are protective factors." (PMID 40837128, 2025).
cyst (1 paper, 2019). A sac-like closed membranous structure that may be empty or contain fluid or amorphous material. "In contrast, BxPC3 cells, which are completely resistant to cyst(e)inase treatment in vivo, were able to maintain aspartate levels at more than 50% of control upon cyst(e)inase treatment but without requiring upregulation of PC activity." (PMID 31231686, 2019).
epilepsy (1 paper, 2021). A brain disorder characterized by episodes of abnormally increased neuronal discharge resulting in transient episodes of sensory or motor neurological dysfunction, or psychic dysfunction. "CA V, providing HCO3− to pyruvate carboxylase, is involved in controlling the proper functioning of this enzyme and, then, its action might have implications for epilepsy." (PMID 34770789, 2021).
Fulminant hepatic failure (1 paper, 2015). Hepatic failure refers to the inability of the liver to perform its normal synthetic and metabolic functions, which can result in coagulopathy and alteration in the mental status of a previously healthy individual. "Reports specify that the presence of BCP mutations affecting HBeAg expression during the acute stage is associated with more severe clinical paths and/or fulminant hepatic failure which emphasizes the need to screen for BCP/PC mutations in infected acute patients." (PMID 26571502, 2015).
Glucose intolerance (1 paper, 2022). Glucose intolerance (GI) can be defined as dysglycemia that comprises both prediabetes and diabetes. "While the loss of pyruvate carboxylase in the liver is tolerated during a 24 h fast and is protective for high fat–induced glucose intolerance, a ketogenic diet causes rapid metabolic decompensation." (PMID 36441025, 2022).
inflammatory bowel disease (1 paper, 2025). A spectrum of small and large bowel inflammatory diseases of unknown etiology. "NADH dehydrogenase [ubiquinone] flavoprotein 2, hydroxymethylglutaryl‐CoA synthase 9, pyruvate carboxylase, apoptosis‐inducing factor 1, and transmembrane protein 70 with inflammatory bowel disease were identified as protective factors." (PMID 40837128, 2025).
inflammatory breast carcinoma (1 paper, 2026). An advanced, invasive breast adenocarcinoma characterized by the presence of distinct changes in the overlying skin. "Through pharmacological and genetic manipulations of inflammatory breast cancer (IBC) and/or triple negative breast cancer (TNBC) cell lines, we identified pyruvate carboxylase (PC) as an E-cadherin effector." (PMID 42039395, 2026).
liver cancer (1 paper, 2023). An epithelial or non-epithelial malignant neoplasm that arises from the liver. "Erianin effectively inhibited the enzyme activity of pyruvate carboxylase (PC), promoted mitochondrial oxidative stress, inhibited glycolysis, inducing insufficient energy required for the proliferation of liver cancer cells." (PMID 37663261, 2023).
neuroblastoma (1 paper, 2021). Neuroblastoma (NB) is the most common solid, extracranial childhood tumor. "We propose that NCT-503 treatment enhances pyruvate carboxylase pathway activity in neuroblastoma cells as an alternative route to fuel the TCA cycle with glucose-derived carbons." (PMID 34192988, 2021).
osteosarcoma (1 paper, 2020). A usually aggressive malignant bone-forming mesenchymal neoplasm, predominantly affecting adolescents and young adults. "We observed that osteosarcoma tissue displays a poor activity of pyruvate carboxylase, since the levels of the citrate isotopologue m+5 were only about 2% (compared to 15% of m+2)." (PMID 32158544, 2020).
overnutrition (1 paper, 2024). An imbalanced nutritional status resulting from excessive intake of nutrients. "Pyruvate cycling is an ATP-consuming cycle that becomes upregulated when the liver is in a high-energy state characteristic of overnutrition, possibly due to activation of pyruvate carboxylase by excess acetyl-CoA." (PMID 38729350, 2024).
pancreatic ductal adenocarcinoma (1 paper, 2023). An infiltrating adenocarcinoma that arises from the epithelial cells of the pancreas. "For example, upon glutaminase (GLS) inhibition in pancreatic ductal adenocarcinoma (PDAC) cells, the upregulation of pyruvate carboxylase (PC), activation of lipid biosynthetic pathways, and alternative pathways involved in glutamate production allowed cells to adapt and regain proliferation." (PMID 37720350, 2023).
periodontitis (1 paper, 2024). An acute or chronic inflammatory process that affects the tissues that surround and support the teeth. "The results of the present study revealed a causal association between periodontitis and medium-chain specific acyl-CoA dehydrogenase (MCAD), malonyl-CoA decarboxylase (MLYCD), glutaredoxin 2 (Grx2), oligoribonuclease (ORN), and pyruvate carboxylase (PC)." (PMID 39063197, 2024).
porphyria (1 paper, 2026). Porphyria is a group of diseases in which substances called porphyrins build up, negatively affecting the skin or nervous system. "Rare absolute contraindications include selected inborn errors of metabolism affecting pyruvate carboxylase activity, carnitine transport or utilisation, fatty acid oxidation pathways, as well as porphyria." (PMID 41486865, 2026).